RUNX3 (RUNX family transcription factor 3)
Diseases named in the same sentence as RUNX3 in open-access papers (continued):
Sharing a sentence is not in itself a finding about the gene and the disease.
gastric cancer (continued). "The inactivation of RUNX3 in a variety of solid tumors has also been identified as an important tumor oncogenic factor.RUNX3 has been reported to act as a tumor suppressor in melanoma, gastric cancer and lung cancer, inhibited tumor progression and metastasis." (PMID 39822248, 2024). "Here, we analyze the role of RUNX3 in gastric cancer cells and establish WNT5A as its downstream target in driving metastasis." (PMID 38240752, 2024). "Compared with normal gastric epithelial cells, gastric cancer cells gradually lose RUNX3 expression as they gain high invasiveness with cancer progression." (PMID 38430423, 2024). "Although we found that RUNX3 functioned as a tumor suppressor in gastric cancer, it was reported that RUNX3 served as an oncogene in epithelial ovarian cancer, basal cell carcinoma, and head and neck squamous cell carcinoma." (PMID 38240752, 2024). "HDAC1 and G9a overexpression inhibits the nuclear localization and RUNX3 expression under hypoxic condition in gastric cancer cells." (PMID 38683453, 2024). "The Runx3−/− mouse stomach epithelium is highly susceptible to the chemical carcinogen N-methyl-N-nitrosourea (MNU) and readily developed invasive stomach cancer following MNU treatment, compared with wild-type mice." (PMID 38240752, 2024). "Complementing these findings, RUNX3 is observed to down-regulate VEGF expression in gastric cancer cells, thereby limiting angiogenesis and impeding tumor growth and metastasis." (PMID 38430423, 2024). "A previous study on gastric cancer cells demonstrated that RUNX3 destabilised hypoxia-inducible factor HIF-1α in the hypoxic microenvironment, thus inhibiting angiogenesis." (PMID 37759525, 2023). "H. pylori CagA binds directly to RUNX3 and promotes its ubiquitination and proteasomal degradation in gastric cancer cells." (PMID 36899853, 2023). "Mechanistically, HOTAIR complexes with Mex3b to ubiquitinate and degrade RUNX3 in gastric cancer cells, leading to increased cancer invasiveness." (PMID 36899853, 2023). "Overexpression of RUNX3 in an array of gastric cancer cell lines resulted in the reduction of MYC proteins in all tested cell lines." (PMID 37400551, 2023). "Chronic H. pylori infection, a class one carcinogen in gastric cancer, has been reported to promote RUNX3 promoter hypermethylation and its subsequent inactivation in gastric cancer." (PMID 36766749, 2023). "JAB1 has been shown to facilitate CSN-mediated proteasomal degradation of RUNX3 in gastric cancer cells." (PMID 36899853, 2023). "HOTAIR, through promoting Mex3b-dependent ubiquitination and degradation of RUNX3, suppresses Claudin1 expression to foster gastric cancer cell invasion and EMT." (PMID 36899853, 2023). "In this regard, HOTAIR/Mex3b promotes gastric cancer tumorigenesis by inhibiting the RUNX3–Claudin1 tumor suppressive axis." (PMID 36899853, 2023). "RUNX3 induces cell cycle arrest and inhibits cell proliferation of gastric cancer cells by inactivating Akt1/β-catenin/cyclin D1 signaling pathway." (PMID 38093179, 2023). "RUNX3 controls neurogenesis in the dorsal root ganglia and cell proliferation in the gastric epithelium and is frequently deleted or silenced in human gastric cancer." (PMID 37965330, 2023). "The observation that RUNX3 hypermethylation occurs more frequently in intestinal-type, relative to diffuse-type, gastric carcinomas, suggests that RUNX3 functions as a gatekeeper of intestinal-type gastric carcinomas." (PMID 36766749, 2023).
gastric cancer (continued). "Mislocalization of the RUNX3 protein in the cytoplasm also affects its tumor suppressor function, as has been reported in colorectal, breast, and gastric cancers." (PMID 36429115, 2022). "Hypoxia-induced microRNAs (miRNAs) have been reported to regulate angiogenesis, apoptosis and cell proliferation in gastric cancer cells through the targeting of RUNX3." (PMID 36231060, 2022). "This was reported in AML and chronic myeloid leukemia (CML), as well as gastric cancer cells, suggesting that the hypermethylation of RUNX3 reduces its expression during cancer development." (PMID 36005134, 2022). "For instance, miR-130a and miR-495 are upregulated under hypoxic conditions and bind to the RUNX3 3′-untranslated region (3′-UTR) to target RUNX3 mRNA translation in gastric cancer cells." (PMID 36231060, 2022). "RUNX3 overexpression in gastric cancer cells can make them more sensitive to chemotherapeutic medicines, whilst its downregulation can make them more resistant to several treatments." (PMID 35522574, 2022). "In gastric cancer, the interaction between RUNX3 and TEAD inhibits the transcription of downstream genes, such as CTGF and CY61." (PMID 36429115, 2022). "In some types of gastric cancer, RUNX3 is regulated at the post-translational level by HMT under hypoxic conditions." (PMID 36231060, 2022). "Recent studies examined the role of RUNX3 in tumor suppression and the prevention of metastasis in cervical cancer, endometrial cancer, and gastric cancer." (PMID 36518886, 2022). "As above, these results are also consistent with previous research that examined the function of RUNX3 in ovarian cancer, gastric cancer, colon cancer, and other cancers." (PMID 36518886, 2022). "Our study provides new insights into the regulation of RUNX3 protein stability under hypoxia and has clinical implications for RUNX3 inactivation during early stages of gastric cancer development." (PMID 33116296, 2021). "The frequent hypermethylation and silencing of RUNX3 in solid tumors—including breast cancer, gastric cancer and hepatocellular carcinoma—indicates a prominent role in solid tumor suppression." (PMID 34831147, 2021). "Transcriptional silencing of RUNX3 by hemizygous deletion or increased DNA methylation in the promoter has been reported in about 60% of human gastric cancers." (PMID 33116296, 2021). "LncRNA GAS5 overexpression enhances the killing effect of NK cell on liver cancer through regulating miR-544/RUNX3.Promotes NK cell cytotoxicity against gastric cancer by regulating miR-18a." (PMID 34295338, 2021). "Subsequently, MT1JP was found as a ceRNA to bind to miR-214-3p to facilitate expression of runt related transcription factor 3 (RUNX3), and suppressed cell proliferation, invasion and migration in gastric cancer cells." (PMID 33557774, 2021). "Another study shows that lncRNA HOTAIR induces Runx3 ubiquitination through the interaction with Mex3b while enhancing gastric cancer (GC) cell proliferation." (PMID 34746238, 2021). "Although we demonstrated the silencing mechanism of RUNX3 at the transcription level under hypoxia, these cell lines suggest an additional molecular mechanism regulating RUNX3 expression under hypoxia in gastric cancer." (PMID 33116296, 2021). "In the present study, we first demonstrated the molecular mechanism of Lys methylation of RUNX3 under hypoxia in gastric cancer, an unexplored mechanism of posttranslational modification (PTM) for RUNX3 activity." (PMID 33116296, 2021). "In gastric cancer, miR-17-5p has been shown to promote cellular proliferation and invasiveness by targeting RUNX3." (PMID 34598688, 2021). "For example, miR-17-5p directly targets RUNX3 and promotes proliferation and invasiveness in gastric cancer." (PMID 34552925, 2021). "Our previous work demonstrated that RUNX3 was downregulated in gastric cancers under hypoxia by epigenetic mechanism involving histone deacetylation and methylation." (PMID 33116296, 2021).
gastric cancer (continued). "We examined protein expression of G9a and RUNX3 under hypoxia in gastric cancer cell and investigated the patterns of exogenously expressed RUNX3 under hypoxia." (PMID 33116296, 2021). "We set 6.4 copies of methylated RUNX3, which was the median copy number in the gastric cancer group, as a tentative cut-off point." (PMID 32224873, 2020). "A very low level of RUNX3 methylation in patients with stage I gastric cancer makes it difficult to compare the methylation level of RUNX3 with lymph-vascular invasion and tumor size." (PMID 32224873, 2020). "The median copy numbers of methylated RUNX3 were 2.8 (range, 0.0 to 18.4) in the control group and 6.4 (range, 0.0 to 26.0) in the gastric cancer group before treatment." (PMID 32224873, 2020). "The E3 ligase MEX-3B was shown to be involved in the ubiquitination of the runt-related transcription factor 3 (RUNX3), leading to its degradation in gastric cancers." (PMID 32717840, 2020). "Methylated RUNX3 is a well-known biomarker of gastric cancer but it is very difficult to detect with conventional bisulfite-based methylation assays when only a small amount of serum is available." (PMID 32224873, 2020). "In the present study, we evaluated the clinical performance of the CORD assay targeting methylated RUNX3 for the detection of early gastric cancer from serum samples." (PMID 32224873, 2020). "We evaluated the sensitivity and specificity of the serum DNA testing of methylated RUNX3 by the CORD assay for the detection of early gastric cancer using 50 patients with early gastric cancer and 61 control individuals." (PMID 32224873, 2020). "The copy number of methylated RUNX3 also remained high in seven patients with gastric cancer after curative treatment." (PMID 32224873, 2020). "As a mediator of TGF-β signaling, RUNX3 has been shown to inhibit EMT that promotes metastasis in gastric cancer and hepatocellular carcinoma cells." (PMID 33298014, 2020). "It is reported that miR-532-5p functions as an oncogenic miRNA in gastric cancer cells by targeting RUNX3 at both transcriptional and translational level in vitro and in vivo." (PMID 31555130, 2019). "Earlier evidence suggests that RUNX3 is inactivated by hyper-methylation of RUNX3 promoter region and by hemizygous deletion in approximately 60% of primary gastric cancers." (PMID 30535344, 2019). "Methylation of genes such as RARB2, APC, CDKN2A, and RUNX3 has been shown to decrease following surgery in breast, esophageal, liver, and gastric cancers." (PMID 31615043, 2019). "In our RNA sequencing study on gastric cancer patients, Runt-related transcription factor-3 (RUNX3) expression was significantly down-regulated in gastric cancer." (PMID 30871613, 2019). "Since the discovery of the potential role of RUNX3 in gastric cancer, RUNX3 has been found to be inactivated in various cancers, including colorectal, liver, lung, prostate, and breast as well as gliomas." (PMID 31467531, 2019). "Studies from our lab in the context of gastric cancer have suggested that RUNX3 delimits DNA binding of TEAD-complex to abrogate pro-tumorigenic activity of YAP-TEAD." (PMID 29581836, 2018). "The results demonstrated that, compared with tissues adjacent to cancer and normal gastric mucosa tissues, the RUNX3 gene in tissues of gastric cancer had lower levels of expression (P<0.01)." (PMID 28828318, 2017). "RUNX3 has multiple functions and was demonstrated to play tumor suppressive roles in numerous human cancers, such as gastric cancer, RCC, colorectal cancer, breast cancer and melanoma." (PMID 29254144, 2017). "This suggests that malnutrition is more prevalent in gastric cancer patients and the severity is closely related to the expression of RUNX3." (PMID 28828318, 2017). "In gastric cancer, RUNX3 cooperates with FoxO3a to participate in the induction of apoptosis by activating Bim." (PMID 28456786, 2017).
gastric cancer (continued). "The low nutritional status of elderly advanced gastric cancer patients with low expressions of RUNX3 can be significantly enhanced by holistic nursing, thereby prolonging survival time." (PMID 28828318, 2017). "Compared with tissues adjacent to cancer and normal gastric tissues, RUNX3 protein in tissues of advanced gastric cancer showed lower levels of expression (P<0.01)." (PMID 28828318, 2017). "Research on the correlation between RUNX3 and the occurrence of gastric cancer has garnered increasing scientific attention." (PMID 28828318, 2017). "H. pylori infection contributes to the loss of expression of the transcription factor related Runt-3 (RUNX3) in gastric cancer through its overmethylation." (PMID 28512631, 2017). "Compared with normal gastric tissue, the expression of RUNX3 gene and protein in tissues of advanced gastric cancer were significantly decreased (P<0.01)." (PMID 28828318, 2017). "Compared with patients with normal or high expressions of RUNX3, the nutritional statuses of advanced gastric cancer patients with low expressions of RUNX3 were lower (P<0.01)." (PMID 28828318, 2017). "The expression of RUNX3 is closely correlated with the occurrence and development of advanced gastric cancer in elderly patients." (PMID 28828318, 2017). "There were relevant reports with miRNA medicated inactivation of RUNX3 such as miR-532-5p in gastric cancer and miR-4295 in gliomas." (PMID 29340016, 2017). "This study aimed to assess the nutritional statuses of elderly patients with advanced gastric cancer, and summarily analyze its relationship with RUNX3 expression level and nursing strategies." (PMID 28828318, 2017). "G9A is a key therapeutic target as it can regulate downstream genes via epigenetic mechanisms to promote cancer, such as the silencing of the tumor suppressor RUNX3 in gastric cancer." (PMID 29145444, 2017). "The expression of RUNX3 gene and RUNX3 protein in elderly patients with advanced gastric cancer were detected by semi-quantitative PCR and western blot, respectively, in this study." (PMID 28828318, 2017). "The aim of this study was to explore the relationship between nutritional status and expression of RUNX3 in gastric cancer cells and to investigate the effects of nursing strategies on the nutritional status of elderly patients with advanced gastric cancer." (PMID 28828318, 2017). "The methylation frequencies at six specific loci (MINT2, MINT31, p14, p16, p73, and Runt-related transcription factor 3(RUNX3)) in EBVaGC were significantly higher in comparison to EBV-negative gastric cancer." (PMID 28757548, 2017). "The expression of RUNX3 is abnormal in most gastric cancer cells and mediates the progression of gastric cancer." (PMID 28828318, 2017). "Patients of the advanced gastric cancer group were divided into a low expression group (n=35) and a normal or high expression group (n=13), according to the expression of RUNX3." (PMID 28828318, 2017). "In the article, RUNX3 is an important transcriptional regulator which found to be frequently hypermethylated at the promoter regions in gastric cancer." (PMID 28144288, 2017). "For instance, the transcription factor Cdx2 can enhance the expression of claudin-3 and -4 in gastric cancer cells, and the transcription factor RUNX3 can enhance the expression of claudin-1 by binding to its promoter region." (PMID 28350854, 2017). "RUNX3 has been identified to play multiple tumor suppressor roles in many kinds of human cancers, including gastric cancer, colorectal cancer, and breast cancer." (PMID 28977878, 2017). "There is a close relationship between the expression of the RUNX3 gene and gastric cancer, indicating that RUNX3 can affect the progression of gastric cancer by regulating the proliferation and migration of gastric cancer cells." (PMID 28828318, 2017).
gastric cancer (continued). "Compared with tissues adjacent to cancer and normal gastric tissues, RUNX3 gene in tissues of advanced gastric cancer showed lower levels of expression of RUNX3 (P<0.01)." (PMID 28828318, 2017). "The results of western blot showed that, compared with tissues adjacent to cancer and normal gastric mucosa tissues, RUNX3 protein in tissues of gastric cancer had lower levels of expression (P<0.01)." (PMID 28828318, 2017). "RUNX3 has been identified as a tumour suppressor gene in a variety of solid tumours including gastric carcinoma, breast carcinoma, hepatocellular cancer and oral squamous-cell carcinoma." (PMID 29340016, 2017). "A recent study demonstrated that miR-495 decreases cell proliferation and tumor angiogenesis by inhibiting the expression and activity of Runt-related transcription factor 3 (RUNX3) in gastric cancer cells." (PMID 27323412, 2016). "Primary gastric cancer specimens express lower levels of RUNX3 due to a combination of a hemizygous deletion and hypermethylation of the RUNX3 promoter region." (PMID 26375442, 2015). "The role of RUNX3 methylation has been intensively studied in gastric cancers; however, data relating CNS tumors are very limited and apply only to small groups of patients." (PMID 25648363, 2015). "The miR-301a-3p had been reported to target MEOX2 in lung cancer, FOXF3, BBC3, PTEN and COL2A1 in breast cancer and RUNX3 in gastric cancer." (PMID 26019136, 2015). "Runx3 expression was frequently downregulated in gastric cancer cells because of promoter hypermethylation." (PMID 26417932, 2015). "In this study, we examined the combination effect of miRNA-130a and miRNA-495 targeting RUNX3 under hypoxic conditions in cell proliferation and angiogenesis in gastric cancer cells." (PMID 26375442, 2015). "The clinicopathological analysis on gastric cancers and premalignant lesions showed that Runx3 hypermethylation was correlated with H. pylori infection." (PMID 26417932, 2015). "miR-130a and miR-495 upregulated under hypoxic conditions that bind to the RUNX3 3′-untranslated region (3′-UTR) were identified in gastric cancer cells by using microarray analysis and bioinformatics programs." (PMID 26375442, 2015). "The RUNX3 expression was also detected in 41 gastric cancer tissues by western blotting, and we found that the expression of miR-130a was inversely correlated with that of RUNX3." (PMID 26134263, 2015). "In this study, we identified miR-130a and miR-495 as potential oncomiR candidates capable of targeting RUNX3, decreasing apoptosis, and increasing cell proliferation in gastric cancer cells." (PMID 26375442, 2015). "The hypermethylation of the CpG island of RUNX3 has been reported in 64% of cases of gastric cancer." (PMID 25997695, 2015). "The Runt-related transcription factor 3 (RUNX3) expression and activity are frequently downregulated by various mechanisms in gastric cancer." (PMID 26375442, 2015). "The results show that miR-130 promotes gastric cancer tumorigenic abilities by targeting RUNX3, and it elucidates the reason for miR-130a acting as an oncogene in gastric cancer." (PMID 26134263, 2015). "In gastric cancer patients, levels of RUNX3 were positively correlated with miR-30a and negatively associated with the levels of vimentin." (PMID 24447545, 2014). "We knocked down miR-30a with an inhibitor of miR-30a in RUNX3-overexpressed gastric cancer cells and detected cell invasion and the expression of vimentin." (PMID 24447545, 2014). "Overexpression of RUNX3 suppressed cell invasion and decreased the protein expression of vimentin in gastric cancer cells and inhibited gastric cancer cell colonization in nude mice." (PMID 24447545, 2014). "Reported target genes of miR-106a include RUNX3, resulting in multidrug resistance in gastric cancer." (PMID 24626163, 2014). "In gastric cancer patients, levels of RUNX3 were positively correlated with miR-30a and negatively associated with vimentin." (PMID 24447545, 2014).